MMP9 (matrix metallopeptidase 9)
Diseases named in the same sentence as MMP9 in open-access papers (continued):
Sharing a sentence is not in itself a finding about the gene and the disease.
astrocytoma (19 papers, 2000 to 2026). "A strong correlation between elevated expression levels of MMP-2, MMP-9, as well as membrane-associated MMPs, with higher grade astrocytomas has been described, suggesting that inhibitors of these MMPs may modulate astrocytoma progression." (PMID 26431549, 2015). "Contrary to their study, our analysis revealed overexpression only in the MMP9 gene exclusively in GBM compared to astrocytomas." (PMID 38474106, 2024). "Tumor necrosis factor (TNF)-related apoptosis-inducing ligand (TRAIL) induced MMP9 expression in human astrocytoma cells through activation of extracellular signal-regulated protein kinase (ERK)." (PMID 27022952, 2016). "To investigate the effect of PODXL on astrocytoma cell invasion, we performed in vitro cell invasion assays and examined the MMP-9 expression level in the two cell lines." (PMID 23596468, 2013). "In conclusion, in the present study it was demonstrated that PODXL promotes astrocytoma cell invasion, potentially through the upregulation of MMP-9 expression in a PI3K-dependent manner." (PMID 23596468, 2013). "In conclusion, we demonstrated that PODXL promotes astrocytoma cell invasion, potentially through upregulating MMP-9 expression in a PI3K-dependent manner." (PMID 23596468, 2013). "The levels of MMP9 expression have also been found to be increased in nasal NK/T-cell lymphoma, malignant astrocytomas, carcinomatous meningitis, and brain metastases." (PMID 20534121, 2010). "Tanshinone IIA inhibited astrocytoma migration by the down-regulation of cellular-myelocytomatosis viral oncogene (c-Myc), Bcl-2, and matrix metalloproteinase-9 (MMP-9) expression, and the up-regulation of transmembrane receptor notch homolog 1 (Notch-1) pathway." (PMID 35897965, 2022). "High dose of Tan IIA was shown to inhibit astrocytoma migration through up-regulating transmembrane receptor notch homolog 1 (Notch-1) pathway and down-regulating matrix metalloproteinase-9 (MMP-9), cellular-myelocytomatosis viral oncogene (c-Myc), and Bcl-2 expression." (PMID 32265690, 2020). "Higher-grade astrocytomas display a sharp increase in MMP-9 transcript levels." (PMID 26431549, 2015). "Recent proteinase profiling studies have demonstrated the over-expression of the serine urokinase-type plasminogen activator (uPA) and its receptor (uPAR), cysteine protease cathepsin B, MMP-2, and MMP-9 in high grade astrocytomas compared with low grade astrocytomas or the normal brain." (PMID 20587068, 2010). "Additionally, our findings that the selective PI3K inhibitor LY eradicated the effect of PODXL overexpression and extended the effect of PODXL knockdown, suggest that PODXL promotes invasion and MMP-9 expression in astrocytoma cells by a PI3K-dependent mechanism." (PMID 23596468, 2013). "For example, MMP9 induced IGFBP2-IGF2 complex proteolysis resulted in the extracellular release of free IGF2 with positive and biologic effect on astrocytoma cellular growth and migration." (PMID 19489099, 2009). "MMP‐9 has been shown to induce IGF‐2/IGFBP2 complex proteolysis resulting in the extracellular release of free IGF‐1 with positive and biological effect on astrocytoma cellular growth and migration." (PMID 29321953, 2018).
clear cell renal cell carcinoma (19 papers, 2013 to 2026). "RT-qPCR analysis validated that MMP9 expression was significantly upregulated in 786 O cells (human renal clear cell carcinoma) compared to HK-2 cells (human renal cortical proximal convoluted tubule cell)." (PMID 40830065, 2025). "MMP9 affect the survival of circulating tumor cells in clear cell renal cell carcinoma by adapting to tumor immune microenvironment." (PMID 38375034, 2024). "Previous studies have confirmed that HMGN5 regulates the expression of MMP2 and MMP9 via c-jun and then contributed to the migration and invasion of clear cell renal cell carcinoma (ccRCC) cells." (PMID 31930127, 2019). "In this study, we focused on the correlation between MMP9 expression and clear cell renal carcinoma (ccRCC)." (PMID 30013825, 2018). "Additionally, western blot analysis confirmed that MMP9 was markedly downregulated in 786 O cells treated with poly-HEMA for 48 h, suggesting an important role for MMP9 in anoikis of renal clear cell carcinoma." (PMID 40830065, 2025). "BCL2 and MMP9 have been found to play significant roles in tumor immunity and may serve as potential novel biomarkers and therapeutic targets for immunotherapy of clear cell renal cell carcinoma (ccRCC)." (PMID 39272451, 2024). "Object: The present study screened ideal lead natural compounds that could target and inhibit matrix metalloproteinase 9 (MMP9) protein from the ZINC database to develop drugs for clear cell renal cell carcinoma (CCRCC)-targeted treatment." (PMID 34607974, 2021). "In renal clear cell carcinoma, ISG20 positively regulates the expression of CCND1, which promotes cell proliferation and upregulates the expression of MMP9, which is involved in the breakdown of the extracellular matrix and promotes metastasis." (PMID 39428941, 2025). "After treatment of clear cell renal cell carcinoma cells with LGK974, the expression levels of β-catenin, cyclin D1, c-Myc, MMP9, and MMP2 were significantly decreased." (PMID 33923996, 2021). "Conversely, it plays an oncogenic role by enhancing matrix metalloproteinase 9 (MMP9) transcription during invasion and metastasis in small cell lung cancer and by activating MMP2 and MMP9 in local and vascular infiltration in clear cell renal cell carcinoma." (PMID 28146423, 2017). "Higher expression of MMP-2 and MMP-9 are found in patients who have kidney clear cell carcinoma metastases when compared to patients without distant metastases." (PMID 31200666, 2019).
coronary atherosclerosis (19 papers, 2007 to 2025). Atherosclerosis of the coronary vasculature. "To further elucidate the impact of the MMP-9 (rs17576) SNV on the degree of coronary atherosclerosis, we examined various CAD-associated risk factors." (PMID 40224343, 2025). "The association of the MMP-9 -1562 C/T polymorphism with cardiovascular disease was found in another Polish study of 110 patients with coronary atherosclerosis." (PMID 26330106, 2015). "Besides, Mendelian randomization analyses showed that rs3918249 and rs11699481 polymorphisms of MMP9 gene were associated with the higher circulatory levels of MMP-9 and the risk of coronary atherosclerosis." (PMID 39528464, 2024). "Accordingly, the aim of this study was to investigate the associations between serum MMP-9 levels, the MMP-9 (rs17576) SNV, the extent of coronary atherosclerosis, and other recognized risk factors in a cohort of Ukrainian CAD patients." (PMID 40224343, 2025). "Furthermore, downregulated FOSB and MMP9 were found under the treatment of Insulin-like growth factor 1 that reduced reduces coronary atherosclerosis." (PMID 40486911, 2025). "In this study, MMP9 expression in EAT of CAD patients was upregulated by proteomics, which was further confirmed by western blot; thus, this protein is intimately linked with coronary artery atherosclerosis, perhaps by coordinating vascular remodeling and vascular smooth muscle migration." (PMID 31534454, 2019). "MMP-9 and TIMP-2 were also found to be elevated in plasma patients with premature coronary atherosclerosis, emphasizing the significance of these biomarkers in assessing coronary vascular health." (PMID 39195176, 2024). "Another author found that patients with CAD had higher MMP‐9 and TIMP‐1 plasma levels but a lower TIMP‐2 level, also both increased MMP‐9 and TIMP‐ 1 plasma levels in premature coronary atherosclerosis patients, but with lower MMP‐3 and TIMP‐2 levels." (PMID 33381894, 2021). "The clinical researches have confirmed that the high MMP-9 expression level was correlated with the premature CAD, unstability of the coronary atherosclerosis plaque, the in-stent restenosis and arterial aneurysm formation." (PMID 27375491, 2016). "In this study, Apoe/MMP-9 double knockout mice had no significant changes in terms of occurrence of sudden death or coronary artery atherosclerosis." (PMID 34848763, 2021).
dementia (19 papers, 2010 to 2025). Loss of intellectual abilities interfering with an individual's social and occupational functions. "Consistent with prior work showing that the ADAS-cog score is not sensitive to subtle cognitive changes associated with the pre-dementia stage, we found that MMP-9 associations with ADAS-cog scores were restricted to AD dementia patients." (PMID 36324151, 2022). "Overall, there was no consistent evidence to suggest a causal effect of CypA or MMP9 eQTL or pQTL PRSs on odds of reporting one or both parents to have dementia or on any of the continuous markers of cognitive function." (PMID 35058547, 2022). "Patients without the apolipoprotein E4 allele (APOE e4), being a factor contributing to AD development, but with the allele T of the -1562C/T polymorphism in the MMP-9 gene were at a lower risk of dementia development when compared to carriers of the allele C [OR = 0.6 (95% CI, 0.3–1.0), p = 0.05]." (PMID 37206663, 2023). "Other studies have demonstrated higher plasma MMP-9 in individuals with dementia than in healthy individuals." (PMID 38431757, 2024). "In our study, ROC curve analysis indicated that MMP-9 and TIMP-1 displayed moderate diagnostic accuracy in discerning dementia due to AD from CU subjects, according to the Swets criterion." (PMID 38891891, 2024). "Our study highlights MMP-9 and TIMP-1 as potential biomarkers with moderate diagnostic accuracy for distinguishing dementia due to AD from cognitively unimpaired individuals." (PMID 38891891, 2024). "The cross-sectional association between free MMP-9 levels and ADAS-cog scores in female AD dementia patients remained significant in the fully adjusted model (β=11.79; 95% CI, 2.45 to 21.12; p=0.015)." (PMID 36324151, 2022). "Consistent with prior evidence of increased plasma MMP-9 levels in AD dementia patients compared to individuals with MCI, we found higher total plasma MMP-9 concentrations in AD patients compared to participants with MCI." (PMID 36324151, 2022). "However, other studies report higher MMP-9 levels in AD compared with other dementia types, highlighting inconsistencies in the findings." (PMID 41009358, 2025). "MMP-9 has been shown to mediate inflammation in nervous tissue in dementia." (PMID 37206663, 2023). "Among all MMPs, MMP-2, -3, -9, and -14 were the major MMPs found in the brain, and high levels of MMP-9 and MMP-2 were observed in patients with frontotemporal dementia (second most common form of dementia)—a disorder often causing significant personality and behavior changes." (PMID 32466129, 2020). "This outlines the presence of a direct pathological link between the molecular markers of dementia and MMP-9 activity, even though MMP-9 is an active substrate for Aβ degradation." (PMID 34566627, 2021). "Moreover, simultaneous examination of MMP-9, MMP-2, and TIMP-1 in the cerebrospinal fluid (CSF) contributed to the ability to differentiate between AD and other types of dementia." (PMID 32466129, 2020). "Our study highlights the changes and potential contributions of several chemokines (CXCL1, CCL3, CXCL5, CXCL6, CCL3, CCL19), interleukins (IL8, IL6-RA, IL18-BP), and other immune markers (OSM, ALCAM, OPG, CHIT1, YKL-40, STAMBP, MMP-9, MMP-10) in the prodromal and dementia phases of AD." (PMID 31694701, 2019). "Furthermore, the simultaneous investigation of MMP9, MMP2, and TIMP1 in CSF might provide the potential to distinguish between different types of dementia." (PMID 35454094, 2022). "We found that higher baseline plasma MMP-9 correlated with worse baseline ADAS-cog scores among female but not male AD dementia patients, but higher baseline MMP-9 levels correlated with deteriorating ADAS-cog scores over time among male but not female AD dementia patients." (PMID 36324151, 2022).
hemorrhagic stroke (19 papers, 2014 to 2025). A stroke caused by a bleed on the brain. "have identified that MMP‐9 acts as a biomarker for predicting hemorrhagic events in MMD, with serum levels >1011 ng/mL being an independent risk factor for MMD‐related hemorrhagic stroke." (PMID 39822761, 2025). "On the other hand, the successful surgical treatment of hemorrhagic stroke complication by means of surgical hematoma evacuation and decompressive craniectomy was related with decreased level of MMP-9 over the course of functional recovery." (PMID 36835040, 2023). "Fresh brain tissue from ischemic and hemorrhagic stroke patients examined within 6 h of death revealed higher levels of MMP-9, compared to control brains." (PMID 26973468, 2016). "MMP-9 plays an important role in ischemic and hemorrhagic stroke, and serum levels significantly increase after SAH." (PMID 27504251, 2016). "Increased expression of MMP-9 of the brain tissue was also observed in patients suffering from hemorrhagic stroke." (PMID 25427630, 2014). "Serum MMP-9 level >1,011 ng/ml is an independent risk factor of MMD hemorrhagic strokes." (PMID 34531816, 2021). "Future studies are needed to verify the predictive value of MMP-9 for hemorrhagic strokes in MMD." (PMID 34531816, 2021). "These pathways, together with induced MMP activity (e.g., MMP9), could be partially shared with hemorrhagic stroke." (PMID 33066304, 2020). "Recent studies performed on a rat model of collagenase-induced hemorrhagic stroke revealed that neutrophil depletion reduced MMP-9 expression, blood vessels disruption, blood-brain barrier leakage, axon damage, and astrocyte and microglial/macrophage activation." (PMID 31514749, 2019). "In hemorrhagic stroke, tissue surrounding the hematoma was shown to have increased levels of MMP-9." (PMID 26973468, 2016). "In Cav-1 knockout mice, there is a reduction in heme oxygenase-1 (HO-1), macrophage inflammatory protein 2, MMP-9, and COX-2 during hemorrhagic stroke, leading to decreased immune cell infiltration and mitigated hemin-induced neuronal toxicity, ultimately improving brain damage." (PMID 38922036, 2024). "Similarly, in hemorrhagic stroke models based on cerebral Hb injection, BBB permeability occurs by peroxinitrite formation following Hb’s reaction with NO or by activation of matrix metalloproteinase-9 (MMP-9) inducing apoptosis in the EC of the BBB." (PMID 37371928, 2023). "The level of MMP-9 increases and VE-cadherin decreases as the age of patients rises, indicating later MMD onsets, higher gelatinase activity, and poorer BBB function the patients might have, which might be related with hemorrhagic stroke presentations." (PMID 34531816, 2021). "However, previous reports on patients with haemorrhagic stroke did not detect an increase of MMP9-positive vessels in contralateral brain sections, in contrast to perihematomal tissue." (PMID 32631441, 2020). "However, microglia cells may also spur the immune reactions after hemorrhagic stroke by releasing of pro-inflammatory mediators such as TNF-α, IL-1β, NOS, or MMP-9 which leads to infiltration of leukocytes and further progression of the tissue damage." (PMID 31514749, 2019).
influenza (19 papers, 2008 to 2026). An acute viral infection of the respiratory tract, occurring in isolated cases, in epidemics, or in pandemics; it is caused by serologically different strains of viruses (influenzaviruses) designated A, B, and C, has a 3-day incubation period, and usually lasts for 3 to 10 days. "In this study, we addressed the contribution of MMP9 during influenza virus pathogenesis, which had been implicated recently by virtue of increased concentrations in the serum of patients with influenza and elevated enzymatic activity in mouse lung homogenates." (PMID 22496659, 2012). "Network pharmacology identified genistein and daidzein as key bioactive constituents targeting hub proteins TNF, AKT1, EGFR, SRC, and MMP9, which mediate pathological process in influenza." (PMID 41957261, 2026). "An experimental model of influenza evidenced MMP9 pathogenesis due to excessive neutrophil migration into the respiratory tract in response to viral replication." (PMID 36139764, 2022). "MALT1 mediates the production of MMP-9 in alveolar macrophages, which is involved in influenza pathogenesis and exacerbates the severity of influenza." (PMID 35467421, 2022). "Matrix metalloproteinase-9 (MMP-9) degrades extracellular matrix and is involved in the pathology of influenza." (PMID 29018444, 2017). "Our study revealed a novel role of MALT1 in regulating alveolar macrophage MMP-9 production and showed that MALT1 deficiency alleviates the severity of influenza." (PMID 29018444, 2017). "Taken together, we demonstrated a novel role of MALT1 in regulating alveolar macrophage MMP-9 production whose presence exacerbates the severity of influenza." (PMID 29018444, 2017). "The level of MMP-9 and MMP-9 to TIMP-1 ratio in blood serum was increased in children with influenza caused encephalopathy, both in the group with worse prognosis and in the group who developed febrile seizures." (PMID 28104930, 2016). "MMP9 expression is required for neutrophil migration in an influenza infection mouse model and also regulated viral replication." (PMID 26284919, 2015). "Since influenza-associated inflammation is initiated and dependent on TLRs, we inquired if TLR signaling was also involved in MMP9-mediated neutrophil recruitment." (PMID 22496659, 2012). "In influenza, the virulent influenza virus infection is characterized by a large number of cell infiltration and severe lung pathology, which is related to the production of oxidative stress and MMP-9." (PMID 34803696, 2021). "Although further studies are required to elucidate the roles of MMPs in respiratory viral infections, it has been shown in a mouse model of severe influenza infection (IAV) that MMP9−/− mice exhibited increased survival and were protected from IAV-induced lung injury." (PMID 33020210, 2020). "Evidence from MMP9-related influenza studies suggests that a more circumspect approach may be required." (PMID 27855162, 2016). "Even though the level of MMP-9 in these patients was comparable to the level of MMP-9 in patients with uncomplicated influenza, the patients with neurological complications had increased MMP-9 to TIMP-1 ratio in comparison to the patients without complications." (PMID 28104930, 2016). "MMP9 is required for neutrophil migration during an influenza infection mouse model." (PMID 26284919, 2015). "In this study, we show a previously unknown contribution of MMP9 to influenza pathogenesis by mediating excessive neutrophil migration into the lung, which not only controls viral replication, but also contributes to morbidity." (PMID 22496659, 2012). "Furthermore, we demonstrated that the mechanism for neutrophil-mediated migration to the respiratory tract in response to influenza required MMP9 and depended on extrinsic TLR-signaling." (PMID 22496659, 2012).